FABP4 (fatty acid binding protein 4)
Diseases named in the same sentence as FABP4 in open-access papers (continued):
Sharing a sentence is not in itself a finding about the gene and the disease.
ovarian carcinoma (continued). "Likewise, adipocytes induce FABP4 expression, promoting metastasis and mediates carboplatin resistance in ovarian cancer cells." (PMID 34095111, 2021). "Overexpression of FABP4 is reported in various types of tumors such as ovarian cancer." (PMID 33194756, 2020). "Upon validation with complementary IHC staining for FFPE HGSOC tissue specimens, we identified six protein biomarkers to predict the prognosis of HGSOC; expression levels of AAT, NFKB, PMVK, VAP1, FABP4, and PF4 in ovarian cancer tissue were associated with PFS." (PMID 32224886, 2020). "Taken together, these studies suggest that targeting FABP4 in ovarian cancer may inhibit the ability to adapt lipid-rich cancer microenvironment and to reduce tumor aggressiveness." (PMID 33194756, 2020). "In addition, a significant decrease in tumor burden was observed in Fabp4−/− mice intraperitoneally xenografted with ovarian cancer cell lines." (PMID 30575815, 2019). "It has also been demonstrated that metastatic ovarian cancer cells may import FAs from the adipocytes through the upregulation of FABP4." (PMID 31847385, 2019). "Moreover, recent work identified the additional functional roles of FABP4 in fatty acid metabolism, angiogenesis, and peritoneal dissemination in ovarian cancer." (PMID 30568223, 2019). "However, our study presents cancer cell specific FABP4 as a crucial player in promoting invasive and infiltrative metastasis in ovarian cancer." (PMID 30050129, 2018). "Here, we examined the biological effects of increased FABP4 expression in ovarian cancer." (PMID 30050129, 2018). "We thus identified tamoxifen as a potential drug of interest that could inhibit FABP4 and affect migration of ovarian cancer cells." (PMID 30050129, 2018). "Hence, we decided to investigate the mechanisms that lead to upregulation of FABP4 in ovarian cancer, as well as its downstream effects that lead to metastasis." (PMID 30050129, 2018). "We next investigated the effects of FABP4 knockdown in orthotopic mouse models of ovarian cancer." (PMID 30050129, 2018). "However, FABP4 regulation and the functional implications of FABP4 overexpression in increasing the metastatic potential of ovarian cancer cells remain to be investigated." (PMID 30050129, 2018). "For instance, CAAs interact metabolically with cancer cells through fatty acid transport via FABP4 in ovarian cancer, while FABP4 is involved in lipid transfer between adipocytes and cancer cells, a process that engages the fatty acid oxidation pathway to aid in cancer progression." (PMID 28929459, 2018). "Ovarian cancer cells that have metastasized to adjacent adipose tissues have upregulated expression of genes encoding fatty acid transport proteins such as CD36 and FABP4, together with other molecules including CD31, CD34, VEGFR1, and VEGFR2." (PMID 28929459, 2018). "Having established the importance of FABP4 as a candidate target for ovarian cancer treatment, we next wished to identify clinically approved drugs that could be used to inhibit FABP4." (PMID 30050129, 2018). "It has been reported that S100A7 forms a complex with FABP4 in human keratinocytes, and adipocyte-derived lipids have previously been shown to promote tumor growth by providing an energy source such as FABP4 in ovarian cancer." (PMID 28629450, 2017). "FABP4 was more abundant in vessels of low-grade than high-grade ovarian carcinomas." (PMID 27568980, 2017). "Furthermore, FABP4 promoted ovarian cancer metastasis via the direct transfer of lipids from adipocytes to invasive cancer cells to provide fatty acids for rapid tumor growth." (PMID 29340091, 2017). "Additionally, FABP4 expression was detected in ovarian cancer cells at the adipocyte-tumor cell interface and FABP4 deficiency substantially impaired metastatic tumor growth in mice." (PMID 25569080, 2015). "Activated ovarian cancer cells by adipocytes highly expressed fatty acid-binding protein 4 (FABP4)." (PMID 24213462, 2012).
ovarian carcinoma (continued). "Furthermore FABP4, a lipid chaperone protein, could promote ovarian cancer metastasis and drug resistance." (PMID 39538125, 2024). "Interestingly, FABP4 expression also promotes carboplatin resistance in human ovarian cancer cells in culture and when xenografted in mice, indicating that adipocyte-induced FABP4 expression is critical to both growth and survival in the presence of chemotherapy in ovarian tumors." (PMID 39284708, 2024). "Another series of experiments with an ovarian cancer model showed that overexpression of FA-binding protein 4 (FABP4) enhanced cancer cell proliferation via transfer of FAs from adipocytes,; conversely, downregulation of FABP4 led to the formation of fewer metastatic nodules." (PMID 37205182, 2023). "Thus, FABP4 is a potential therapeutic target for ovarian cancer." (PMID 35216285, 2022). "Indeed, a recent study has identified tamoxifen as a potential drug of interest that could inhibit FABP4 and subsequently affect migration of ovarian cancer cells." (PMID 31092908, 2019). "We checked whether it can be used to target FABP4 in ovarian cancer cells." (PMID 30050129, 2018). "FABP4 inhibitors such as BMS309403 significantly inhibit tumor growth and enhance chemosensitivity in ovarian cancer models." (PMID 40717587, 2025). "The inhibition of FABP4 by CRISPR and siRNA reduced the capacity of adipocyte cocultured ovarian cancer cells to accumulated lipids, and with the impact of this, adipocyte‐relevant β‐oxidation, ROS generation and lipid peroxidation were affected." (PMID 37605299, 2023). "Therefore, some molecular inhibitors targeting FABP4 might block its function and bring a promising future for ovarian cancer therapy, such as BMS309403, which was initially used to treat atherosclerosis and type 2 diabetes and has been proven to increase platinum‐based drug sensitivity in vivo." (PMID 37605299, 2023). "The functional consequence of this was shown to be resistance to carboplatin, as inhibition of FABP4 with BMS309403 shifted IC50 to Carbpoplatin in PEO1 and PEO4 human ovarian cancer cell lines." (PMID 35565396, 2022). "Based on TCGA, higher FABP4 and LPL and lower TFAM expression indicated poorer overall survival in patients with ovarian cancer." (PMID 36012230, 2022). "And, a small-molecule inhibitor of FABP4 (BMS309403) efficiently blocked early metastasis and reduced tumour burden in an orthotropic mouse model of ovarian cancer." (PMID 35198079, 2022). "Accordingly, targeting FABP4 with the FABP-specific inhibitor BMS309403 significantly reduced cancer cell invasiveness and tumor burden in prostate and ovarian cancer models." (PMID 36497485, 2022). "Their findings showed ovarian cancer cells cocultured with adipocytes had elevated CD36 and FABP4 expression, whereas knockout of FABP4 resulted in inhibition of several tumorigenic pathways including proliferative and migration in ovarian cancer cells." (PMID 36428985, 2022). "Fatty acid-binding protein 4 is upregulated in omental metastases as compared to primary ovarian tumors, and FABP4 expression is present in ovarian cancer cells at the adipocyte-tumor cell interface." (PMID 23109879, 2012). "Moreover, inhibition of FABP4 by its small molecule inhibitor, BMS309403, reduced the tumor burden and highly increased the sensitivity of ovarian cancer cells to carboplatin, both in vitro as well as in vivo." (PMID 41065381, 2025). "In addition, the pro-inflammatory cytokine IL-17A promotes the expression of STAT3 mediating fatty acids binding protein 4 (FABP4), which acts synergistically with fatty acid receptor CD36 to initiate the uptake of fatty acids to fuel ovarian cancer growth." (PMID 38245798, 2024).
ovarian carcinoma (continued). "A CRISPR-mediated knockdown of FABP4 resulted in a significant decrease in the metastatic tumour burden and FABP4 inhibition using BMS309403-sensitised ovarian cancer cells to carboplatin, indicating that lipid uptake mediated by FABP4 contributes to chemoresistance in this system." (PMID 38610991, 2024). "Therefore, the high expression of FABP4 can regulate various metabolites such as FA oxidation (FAO) and lysophospholipids and can lead to metastases in ovarian cancer." (PMID 36613455, 2022). "Multiple fatty acids and enzymes involved in fatty acid metabolism, such as fatty acid-binding protein 4 (FABP4), CD36 and stearoyl-CoA desaturase 1 (SCD1), significantly enhance ovarian cancer proliferation, survival, drug resistance and metastasis, and even contribute to stemness maintenance." (PMID 34820325, 2021). "Moreover, FABP4 has been reported to serve as a target of the VEGF/VEGFR2 signaling pathway in endothelial cells and affects vascular sprouting in ovarian cancer." (PMID 34685761, 2021). "Unlike the study in ovarian cancer, we did not observe FABP4 significant de novo expression in human tumor hepatocytes, suggesting that FABP4 produced by the endothelial cells exerts pro-oncogenic effects on hepatocytes during liver carcinogenesis." (PMID 30575815, 2019). "Among them, adipose-derived FABP4 and FABP5 are identified as critical proteins particularly in lipid-related metabolic processes upon their overexpression in human malignancies including breast, prostate, colorectal, and ovarian cancers." (PMID 28929459, 2018). "In this study, a total of 31 high-grade ovarian cancer tissue samples were analyzed by DESI-MSI in both negative and positive ion modes to investigate a broad range of lipid and metabolites related to FABP4 expression." (PMID 30050129, 2018). "Notably, the present extracellular flux analysis showed that the pharmacological inhibition of FABP4, FABP5, and PPARγ significantly ameliorated the reduced maximum respiration in ovarian carcinoma cell lines without affecting basal respiration." (PMID 40429934, 2025).
Hepatic steatosis (55 papers, 2011 to 2025). Steatosis is a term used to denote lipid accumulation within hepatocytes. "Their findings showed that the circulating FABP4 directly influenced liver malfunction, consequently leading to the progress of metabolic dysfunction‐associated fatty liver disease (MAFLD)." (PMID 39527497, 2024). "Among the adipocyte-derived molecules, fatty acid binding protein 4 (FABP4) has been recently associated with fatty liver and additional features of advanced stages of MAFLD." (PMID 35052876, 2022). "Whereas the serum FABP4 levels were found to be inversely associated with liver steatosis in a study performed in an elderly population (> 65 years), others have shown increased serum FABP4 levels in non-elderly MAFLD patients." (PMID 35052876, 2022). "Imipramine increases fatty liver scores and is linked to adipogenesis in the liver, including FABP4 and SREBP1 mRNA levels, in addition to adiponectin, FASN, and PNPLA3 activation." (PMID 34564583, 2021). "Crude and adjusted models used to assess the association between the serum FABP4 and liver steatosis." (PMID 34966292, 2021). "The use of FABP4 as an indicator of liver steatosis would be a diagnostic advantage over image-based methods, since this well-established non-invasive method would reduce patient discomfort and improve cost-effectiveness." (PMID 34966292, 2021). "In this work, we explore the potential associations between serum FABP4 and liver steatosis assessed by FLI in individuals at increased cardiometabolic risk." (PMID 34966292, 2021). "Multivariable regression models were used to examine the associations of FABP4 with fatty liver after adjusting for demographic and clinical characteristics." (PMID 34966292, 2021). "After adjustment for age and gender (Model 1) and for age, gender, glucose, triglycerides, apoA1, apoB100, and AST (Model 2), the associations between FABP4 and liver steatosis were significant in all the studied groups, including obese patients." (PMID 34966292, 2021). "First, the cross-sectional design precludes stablishing causal relationships between serum FABP4 and liver steatosis." (PMID 34966292, 2021). "In summary, we showed that a loss of FABP4/5 resulted in hyperketotic hypoglycemia and marked hepatic steatosis during prolonged fasting." (PMID 24244493, 2013). "We identified 78 secreted proteins that were positively associated with liver steatosis area, with the top hits including fatty acid binding protein 4 (FABP4), kallistatin (SERPINA4), perlecan (HSPG2); all have known roles in lipid metabolism and driving MASLD progression." (PMID 40250425, 2025). "In addition, we analyzed SREBP1 and FABP4 mRNA expressions and discovered them to be associated with the expression of genes participating in lipid storage, hepatic steatosis, hepatic lipogenesis, and NAFLD pathogenesis." (PMID 34564583, 2021). "In addition, SREBP1 and FABP4 mRNA expression are associated with the expression of genes participating in lipid storage, hepatic steatosis, hepatic lipogenesis, and NAFLD pathogenesis." (PMID 34768813, 2021). "Moreover, multivariate logistic regression models showed that serum FABP4 was independently associated with likelihood for liver steatosis in metabolic patients." (PMID 34966292, 2021). "In MASLD, FABP4 overexpression promotes the uptake of FFAs and the synthesis of triglycerides (TGs), leading to hepatic steatosis, while also inhibiting fatty acid β-oxidation, exacerbating lipid accumulation." (PMID 41035773, 2025). "In previous studies, it was found that the serum FABP4 level in MASLD was positively correlated with the severity of hepatic steatosis." (PMID 40435176, 2025). "We’ve shown in previous studies that antibody-mediated neutralization of FABP4 improves metabolic health in obese mice by lowering hepatic glucose production, improving insulin sensitivity, and reducing hepatic steatosis." (PMID 39843629, 2025).
Hepatic steatosis (continued). "Ethanol-induced liver steatosis promotes de novo FABP4 synthesis and release from hepatocytes, and FABP4 stimulates HCC cell expansion (proliferation and migration) in vitro." (PMID 38672422, 2024). "The reduction in FABP4 expression, lipid accumulation, and inflammation by fatty acids was also observed in both HepG2 and Drosophila melanogaster models of liver steatosis treated with hydroethanolic extract of Lampaya medicinalis Phil." (PMID 35052876, 2022). "Theobromine, a methylxanthine present in cocoa with anti-oxidant, anti-inflammatory, and anti-microbial activities, mitigated liver steatosis and reduced the liver FABP4 expression in obese mice." (PMID 35052876, 2022). "Dietary sphingomyelin attenuated hepatic steatosis potentially by downregulating the liver expression of several PPARγ-related genes, including FABP4." (PMID 35052876, 2022). "We also analyzed the mRNA expression of FABP4 and SREBP1, which is linked to liver lipid storage, liver steatosis, liver lipogenesis, and NAFLD pathogenesis." (PMID 33809508, 2021). "Fatty liver was assessed by FLI which is a subrogated of imaging techniques; however, further validation by imaging techniques and/or liver biopsy is warranted before to fully consider serum FABP4 as a realistic option for liver steatosis determination." (PMID 34966292, 2021). "In line with our previous data, the serum FABP4 levels were increased in patients with liver steatosis." (PMID 34966292, 2021). "Then, univariate and multivariate logistic binary regression models were performed to assess the risk of liver steatosis (i.e., FLI ≥ 60) based on the serum FABP4 levels." (PMID 34966292, 2021). "The FABP4 inhibitor BMS309403 ameliorated hepatic steatosis, macrophage infiltration, and cellular ballooning of hepatocytes in mice fed with high-fat, high-cholesterol diet." (PMID 32899418, 2020). "As illustrated by the analysis of Cav1, Fabp4, and Cd36 expressions and their relations with hepatic steatosis, the liver has a robust metabolic network that includes multiple regulators contributing its plasticity in coping with the challenge of MF diet." (PMID 29266667, 2018). "Here we showed that deletion of FABP4/5 resulted in a marked perturbation of metabolism in response to prolonged fasting, including hyperketotic hypoglycemia and hepatic steatosis." (PMID 24244493, 2013). "In this study, we showed that deletion of FABP4/5 resulted in a marked perturbation of metabolism in response to prolonged fasting, including hyperketotic hypoglycemia and prominent hepatic steatosis." (PMID 24244493, 2013). "In addition, donor grafts in the FABP4 high-expression group were often accompanied by liver steatosis (27.3 vs. 9.1%, P < 0.05)." (PMID 38341383, 2024). "Moreover, the reduction in the liver expression of FABP4 by the ubiquitous miR-100 overexpression was in line with the effect of this molecule protecting from high fat diet-induced liver steatosis." (PMID 35052876, 2022). "In addition, long-term (8–17 weeks) supplementation of AMF suppresses hepatic steatosis with decreasing lipogenesis-related gene expression, including Cebpa, Fabp4, and Slc27a4 in HFD-fed mice." (PMID 35454963, 2022). "However, SR treatment attenuated HFD-induced hepatic steatosis by suppressing TG contents and the expression of fatty acid transport- and lipogenesis-related genes including Fabp1, Fabp4, Slc27a5, Pparg, Mlxipl, Srebf1, Srebf2, Fas, Dgat1, and Dgat2." (PMID 35454963, 2022). "Additionally, the FABP4 expression was increased in hepatocellular carcinoma with liver steatosis, thus suggesting an active role of this molecule in the progression to end-stage liver disease." (PMID 35052876, 2022). "Therefore, we believe that doxepin contributed to fatty liver disease development through the activation of liver steatosis genes (FABP4 and SREBP1), which then led to significant increases in ALT and AST levels." (PMID 33809508, 2021).